CCL5 (C-C motif chemokine ligand 5)
Diseases named in the same sentence as CCL5 in open-access papers (continued):
Sharing a sentence is not in itself a finding about the gene and the disease.
lung fibrosis (8 papers, 2018 to 2025). "In mice lungs, Ccl5 is produced after bleomycin instillation, associated with the influx of Ccr5+ IFNγ-producing γδ T cells, attenuating lung fibrosis in Ackr2-/- mice." (PMID 39768150, 2024). "CCL5 is known to be a profibrotic SASP while increased expression of CXCL2 is strongly associated with radiotherapy-induced lung fibrosis." (PMID 37460469, 2023). "Elevated Ccl5 levels are associated with the influx of Ccr5+ IFNγ-producing γδ T cells, mitigating lethality and lung fibrosis in Ackr2-/- mice, revealing a potential role of CCL5 counterbalancing pulmonary fibrosis triggered by bleomycin." (PMID 39768150, 2024). "Chemokines CXCL5 and CCL5 are known to play a role in leukocyte chemotaxis during inflammation of the lungs and CXCL5 has been associated with idiopathic pulmonary fibrosis." (PMID 37460469, 2023). "Similarly, CCL5 is expressed by alveolar macrophages, macrophages (CD68+), and eosinophils as key sources in fibrosing alveolitis, with a positive correlation between CCL5 levels and eosinophils in pulmonary fibrosis." (PMID 39768150, 2024). "Further studies are required to clarify the precise role of CCL5 in pulmonary fibrosis." (PMID 39768150, 2024). "Notably, CCL2 and CCL5 upregulation was found to precede skin and lung fibrosis in a mouse model that recapitulates the pathology of SSc53." (PMID 29619245, 2018). "Like CCL5 and CXCL9, MDK is a profibrotic cytokine, demonstrated by its role in murine models of pulmonary fibrosis and its use as a biomarker in idiopathic pulmonary fibrosis." (PMID 39989459, 2025). "For instance, the cytokines TNF-α, IL-1α, IL-1β, and IL-6, and the chemokines CCL2 (MCP-1), CCL5 (RANTES), and CXCL2, have been shown to play pro-fibrotic roles in bleomycin-induced lung fibrosis in mice and in certain human fibrotic lung diseases, such as IPF and asbestosis." (PMID 32185174, 2020).
lupus nephritis (8 papers, 2006 to 2025). Glomerulonephritis in the context of systemic lupus erythematosus. "In patients with FSGS, IgA nephropathy (IgAN), and lupus nephritis (LN), CCL5 was highly expressed in the glomeruli and showed a capillary pattern that colocalized with synaptopodin, a podocyte-specific marker." (PMID 40986444, 2025). "CCR1 is a member of the β-chemokine receptor family and can interact with numerous ligands, such as CCL5, and suppressing CCR1 could improve lupus nephritis progression in New Zealand black/white mice." (PMID 37313407, 2023). "Our data imply that CCL5 and CCL8 might be good targets for improving the therapeutic efficacy of MSCs in ameliorating lupus nephritis." (PMID 37567910, 2023).
ovarian tumor (8 papers, 2008 to 2022). "In our system, the SASP program triggered by cisplatin therapy in Brca1-deficient ovarian tumors was limited to Ccl5, Cxcl10, and Il6 of the factors examined." (PMID 35082152, 2022). "On the other hand, the pathway can activate IRF3 and significantly increase the expression of CCL5 and CXCL10, which leads to T cell recruitment and enhances the function of lymphocytes in ovarian tumors." (PMID 34620163, 2021). "Several inflammatory molecules, including RANTES/CCL5, MCP-1/CCL2, and IL-6 were upregulated after transfection of murine ovarian tumor cells O/N with poly (I:C) (10 μg/ml), compared to the untreated cell supernatants." (PMID 30613350, 2018). "A recent study by Dangaj revealed that induced CCL5 and CXCL9 by macrophages could enhance the infiltration of immunoreactive CD8+ T cells into ovarian tumor and promote the overall survival of patients." (PMID 35359417, 2022). "We were not able to detect CCL5 production from NCSLCs within the ovarian tumor mass or in vitro cell culture." (PMID 25788271, 2015).
pancreatitis (8 papers, 2008 to 2025). Inflammation of the pancreas. "Blocking CCL5 or clearing macrophages was effective in reducing MLN4924-enhanced pancreatitis and fibrosis." (PMID 40959082, 2025). "MLN4924 was found to promote the infiltration of M2 macrophages by mediating CCL5, enhancing pancreatitis activity." (PMID 40959082, 2025). "The increased M2 macrophage infiltration, mediated by the upregulated chemokine (C-C motif) ligand 5 (CCL5), is responsible for the enhanced pancreatitis-promoting activity of MLN4924." (PMID 33723230, 2021). "PP2 can reduce macrophage inflammatory protein-2 (MIP-2), MCP-1, MIP-1α, and CCL-5 levels in the inflammation model of acute-pancreatitis-like changes." (PMID 31293574, 2019). "Vice versa, previous studies could show that the secretion of CCL5 along with TNF-α by macrophages induced acinar-to-ductal metaplasia in pancreatitis, pointing to their role in early malignant transformation." (PMID 40282185, 2025). "Clinically, UBE2M expression remarkably decreases in human CP tissues compared with normal specimens and the levels of CCL5 and M2 marker CD163 are negatively correlated with UBE2M intensity, suggesting that neddylation is involved in the pathogenesis of pancreatitis." (PMID 33723230, 2021). "Besides the observation that CCL5 is produced by PDAC cells in the same manner as CCL2, a recent report elegantly showed that the secretion of RANTES and TNF-α through macrophages secrete RANTES/CCL5 and TNF-α in pancreatitis induced acinar-to-ductal metaplasia (ADM)." (PMID 31561620, 2019).
respiratory infections (8 papers, 2011 to 2025). "HCoV-OC43, a common human coronavirus, typically causes mild respiratory infections but can induce cytokine and chemokine responses in infected individuals, such as IL6, TNF-α, IL-8, CCL2 (MCP-1), and CCL5." (PMID 40872743, 2025). "The chemokine CCL5 has been well studied in recruitment of activated natural killer (NK) cells and CD8+ T cells as well as macrophages in respiratory infections and malignancy." (PMID 33521616, 2021). "A number of the genes in this signature have known connections to the immune response and the outcome of respiratory infections, e.g., genes for the chemokines osteopontin (SPP1) and RANTES (CCL5) and the chemokine receptor CCR2." (PMID 22189154, 2011).
sarcoma (8 papers, 2007 to 2025). A usually aggressive malignant neoplasm of the soft tissue or bone. "Furthermore, we determined in a syngeneic sarcoma mouse model that radiation up-regulates IRF3, IFNβ, and the T cell chemokines CCL2 and CCL5 in the tumor microenvironment, which are associated with activation and increased infiltration of Th1/Tc1 T cells in the tumor microenvironment." (PMID 27014915, 2016).
Cerebral ischemia (7 papers, 2011 to 2025). Restriction of arterial blood supply to the brain associated with insufficient oxygenation to support the metabolic requirements of the tissue. "CCL2 and CCL5 are amongst chemokines that have a dual function in the pathophysiology of cerebral ischemia." (PMID 38861234, 2025). "CCL5 deletion reduces infarct volume in cerebral ischemia, and CCR5 blockade improves locomotor function in a murine model of SCI." (PMID 32155215, 2020). "In addition, many enriched inflammatory markers after cerebral ischemia, including interleukins IL-11 and IL-6, chemokines (Ccl4, Ccl2, Ccl5) and serum amyloid A (Saa3), were observed to be up-regulated consistent with reports elsewhere." (PMID 29896414, 2018). "Postmortem studies on animals and humans have demonstrated that cerebral ischemia initiates the expression of various chemokine classes in the brain, such as CCL2, CCL3, CCL5, CXCL8, CXCL10, and CXCL12." (PMID 38861234, 2025). "Cerebral ischemia induced a transient increase of TNF, IL-1β, IL-6, CXCL1, and CCL5 at day 1 post-pMCAO, corresponding to the peak of pro-inflammatory cytokines typically observed in this model." (PMID 38142915, 2024). "Following cerebral ischemia, a cascade of inflammatory mediators including cytokines (TNF, IL-1α, IL-1β, IL-6, IL-10, TGFβ1) and chemokines (MCP-1 [CCL2], Mip-1α [CCL3], RANTES [CCL5]) is initiated." (PMID 22028848, 2011).
experimental autoimmune encephalomyelitis (7 papers, 2007 to 2024). An autoimmune demyelinating disease of the central nervous system that is produced experimentally in animals by the injection of homogenized brain or spinal cord in Freund's adjuvant. "Furthermore, combined neutralization of all three known CCR5 ligands (CCL3, CCL4, CCL5) has been shown to ameliorate the course, i.e., reduce disease activity, in MS animal models of experimental autoimmune encephalomyelitis." (PMID 33324890, 2019). "Lif KO animals have increased expression of CXCL1, GM-CSF, RANTES/CCL5 and MIP-1β/CCL3 early during an experimental autoimmune encephalomyelitis model and reduced CCL2, CCL3, and CXCL10 at a later stage of the disease." (PMID 25277705, 2014).
Hyperglycemia (7 papers, 2018 to 2025). An increased concentration of glucose in the blood. "While hyperglycaemia induced an increase in Ccl5 gene expression, Adam17 deletion in endothelial cells attenuates Ccl5 upregulation in diabetic mice." (PMID 34073747, 2021). "Hyperglycemia-induced inflammatory and oxidative stress can cause substaintial transcriptional changes in the cells, resulting in an augmented production of cytokines, including several inflammatory mediators (MCP-1 and CCL5)." (PMID 30308936, 2018). "Hyperglycemia leads to an enhanced expression of chemokines in kidney tissue, such as CCL2, CCL3, CCL4, CCL5, and CXCL12, involving in immune cell recruitment and modulating the inflammation." (PMID 40046045, 2025). "Many studies suggest that an increase in serum levels of CCL5 occurs in T2DM and are closely related to postprandial hyperglycemia." (PMID 35844380, 2022). "For example, hyperglycemia can stimulate the secretion of CCL2, CCL5, and CXCL12, through podocytes and tubular cells, as reported in mouse models and DN patients, which contributes to proteinuria and glomerulosclerosis." (PMID 34221188, 2021). "Real-time PCR demonstrated that ARPE-19 cells responded to either cytokines or hyperglycemia by upregulating proinflammatory genes such as cytokines (IL-1β and IL-6) and chemokines (CCL2, CCL5) as well as VEGF, an established inducer of vascular leakage." (PMID 31344857, 2019).
lymph node metastasis (7 papers, 2015 to 2024). "CCL5 was positively associated with axillary lymph node metastasis and poor prognostic predictors of BRCA, which was mainly mediated through CCR5/Treg cells." (PMID 38438469, 2024). "In contrast, CCL5 immunoreactivity was negatively correlated with pT and lymph node metastasis in the CCR5-positive group." (PMID 33671956, 2021). "Furthermore, in a previous immunohistochemical study using 40 triple-negative breast cancer (TNBC) tissues, CCL5 immunoreactivity in peritumoral adipocytes was significantly correlated with lymph node metastasis, distant metastases and a worse prognosis in TNBC patients." (PMID 33671956, 2021). "In the CCR1-negative/CCR3-positive/CCR5-negative group, CCL5 immunoreactivity was significantly correlated with the pT, histological grade, Ki67 LI and MVD and tended to be correlated with lymph node metastasis while negatively correlated with the ER and PR." (PMID 33671956, 2021). "CCL5 affected tumor progression through CCR5, and the T-cell-related immune pathway may be the main pathway; the CD4+/CD8+, CCR5+/CD4+ and Treg/CCR5+ cell ratios were significantly increased in the lymph node metastasis group." (PMID 36033472, 2022). "However, the expression of CCL5 was not related to the other clinical factors including gender, age, clinical TNM stage, tumor differentiation, lymph node metastasis, or tumor length." (PMID 26317795, 2015). "CCL5 immunoreactivity was not correlated with any clinicopathological factors in the CCR1-positive group (n = 21), while it was negatively correlated with pathological T factor (pT) (p = 0.037) and lymph node metastasis (p = 0.024) in the CCR5-positive group (n = 45)." (PMID 33671956, 2021).
metastatic melanoma (7 papers, 2015 to 2025). A melanoma that has spread from its primary site to another anatomic site. "The infiltration of these subsets correlates with ICI response in metastatic melanoma, therefore addition of CCL5 blockade to current ICI strategies could impact the ICI response negatively." (PMID 40897819, 2025). "A study looking at metastatic melanoma biopsies showed that up-regulation of several chemokines, including CCL2, CCL3, CCL4, CCL5, CXCL9, and CXCL10 could be correlated with the presence of T cells in the tumor." (PMID 34207884, 2021).
metastatic tumors (7 papers, 2015 to 2024). "Moreover, through the metastatic tumor model, we found that CCL5 can increase the number of renal cancer CTCs, promote EMT, and enhance lung metastasis." (PMID 39227943, 2024). "Highly elevated expression of chemokine (C-C motif) ligand 5 (CCL5) and its receptors chemokine (C-C motif) receptor (CCR) 1/3/5 are observed in clinical and murine metastatic tumor tissues from epithelial ovarian carcinomas." (PMID 25788271, 2015).
osteoporosis (7 papers, 2023 to 2025). A condition of reduced bone mass, with decreased cortical thickness and a decrease in the number and size of the trabeculae of cancellous bone (but normal chemical composition), resulting in increased fracture incidence. "Dysregulation of the CCL5/CCL5 ratio is associated with elevated serum levels of CCL2 in osteoporosis patients." (PMID 41416066, 2025). "In osteoporosis, chemokines that affect osteoblast and osteoclast activity include CCL5, CCL3, and CCL4." (PMID 41416066, 2025). "Elevated circulating levels of CCL2, CCL3, CCL4, and CCL5 have been reported in patients with osteoporosis, suggesting that excessive chemokine signaling may enhance osteoclast recruitment and inflammatory bone resorption." (PMID 41416066, 2025). "In osteoporosis, dysregulation of the CCL2/CCL5 ratio is associated with disease progression and may contribute to the pathophysiology of bone loss." (PMID 41416066, 2025). "According to previous research, the increase in serum CCL5 levels may specifically reflect the rate of bone metabolism in osteoporosis-prone individuals." (PMID 38003358, 2023). "In the final stop of this tour de force of study, the authors demonstrated as a proof-of-principle of therapeutic potential that local delivery of IL-33 and CCL5 (separately) enhanced bone mass and function in the OVX rat model for osteoporosis." (PMID 41365059, 2025). "In osteoporosis and other metabolic bone disorders, dysregulation of chemokine networks—particularly imbalances such as the CCL2/CCL5 ratio—has emerged as a critical factor driving disease progression and bone loss." (PMID 41416066, 2025). "Paradoxically, CCL5, along with CCL2, CCL3, and CCL4, is found to be elevated in patients with osteoporosis." (PMID 41365059, 2025).
rectal cancer (7 papers, 2017 to 2023). A primary or metastatic malignant neoplasm that affects the rectum. "CircABCB10 regulates ferroptosis and apoptosis in rectal cancer cells through the miR-326/CCL5 axis." (PMID 37332354, 2023). "For example, CircABCB10 inhibits ferroptosis and apoptosis of rectal cancer cells by regulating the miR-326/CCL5 axis, providing a potential therapeutic target for the treatment of rectal cancer." (PMID 35688814, 2022). "Interference with circABCB10 suppressed the cell ferroptosis by regulating the miR-326/C–C motif chemokine ligand 5 (CCL5) axis in rectal cancer." (PMID 34381023, 2021). "CircABCB10 and CCL5 were upregulated but miR-326 was downregulated in rectal cancer." (PMID 34381023, 2021). "For example, knockdown of circular ATP binding cassette subfamily B member 10 (circABCB10) promoted lipid ROS production and subsequent ferroptosis by regulating the miR-326/CCL5 axis in rectal cancer, indicating circABCB10 as a promising therapeutic target for rectal cancer." (PMID 35006436, 2020).
type 1 diabetes (7 papers, 2015 to 2024). "Another study also focused on SNPs in Ccl5 that were associated with reduced serum levels of this chemokine, as a correlate of protection for type 1 diabetes." (PMID 32678841, 2020). "The analysis revealed that in patients with type 1 diabetes (n = 42) CCL5 treated Tregs more efficiently suppressed the production of IFN-γ by effector T lymphocytes compared to Tregs “not-stimulated” with CCL5." (PMID 38937380, 2024). "In this study, we examined the role of the CCR5/CCL5 axis in regulating inflammatory response and its impact on regulatory T cells in type 1 diabetes (T1D)." (PMID 38937380, 2024). "Taking that all into consideration, we have tried to define the in vitro effect of CCL5 on the suppressive potential of magnetically sorted Tregs from patients with type 1 diabetes." (PMID 38937380, 2024). "Our results suggest that the CCR5/CCL5-dependent Treg recruitment to inflammation site in patients with type 1 diabetes may be impaired; however, a larger group of patients needs to be assessed to confirm this observation." (PMID 38937380, 2024). "In line with previous studies, our findings support the notion that dysregulation of the CCR5/CCL5 axis contributes to the development and progression of type 1 diabetes (T1D) by modulating Treg-dependent immune responses." (PMID 38937380, 2024). "Therefore, we investigated whether the CCR5/CCL5 axis functions properly in type 1 diabetes patients in terms of Treg lymphocyte migration." (PMID 38937380, 2024). "CCL5 and CCL2 chemokines were shown to be significantly elevated in the type 1 diabetes group vs. controls." (PMID 38937380, 2024). "It is known that CCL5 (RANTES, the CCR5 ligand) can direct recruitment of immune cells to inflammation sites or to autoimmune targets that may contribute to type-1 diabetic development." (PMID 26596471, 2015). "MIP-1α and RANTES/CCL5 have the potential to promote β-cell proliferation, although to date this has only been demonstrated when they are secreted, along with other cytokines/chemokines, by T cells that infiltrate pancreatic islets in type 1 diabetes or insulitis." (PMID 35628332, 2022).
unstable angina (7 papers, 2015 to 2025). "CX3CR1, (CCL5/RANTES) and CC chemokine ligand-18 (CCL18/ PARC) are closely related to refractory unstable angina and can be used as a specific marker, while CX3CL1 is used as a marker of response to statin therapy." (PMID 31934638, 2019). "On the other hand, concentrations and mRNA expression levels of CCL2, CCL5, and CX3CL1 have also been evaluated in patients with acute myocardial infarction and unstable angina, patients with stable angina, and patients without coronary heart disease." (PMID 40508161, 2025).
unstable angina pectoris (7 papers, 2009 to 2019). "Recently, we reported elevated serum levels of CCL5/RANTES and CCL18/PARC in a small patient cohort consisting of subjects with unstable angina pectoris and both chemokines were identified as markers of refractory UAP." (PMID 23029252, 2012).
acne (6 papers, 2019 to 2025). An inflammatory process of the sebaceous glands which is characterized by comedones, nodules, papules and/or pustules on the skin. "For example, Maraviroc, an FDA-approved CCR5 antagonist for HIV, blocks the receptor for CCL5 and may reduce the chemotactic effects of CCL5 in acne lesions." (PMID 40401196, 2025). "While dermcidin, granulysin (GNLY), RANTES (CCL5), perforin, CXCL9, and two neuropeptides (substance P and chromogranin B) remained unaffected either in untreated acne patients as well as by isotretinoin treatment." (PMID 39744637, 2024).